TTF1 (transcription termination factor 1)
Diseases named in the same sentence as TTF1 in open-access papers (continued):
Sharing a sentence is not in itself a finding about the gene and the disease.
non-small cell lung carcinoma (continued). "The combined use of antibodies TTF-1 and cytokeratin 7 (CK7) for ADC and p63 with high molecular weight keratins (CK5/6) for SCC provides a very reliable distinction between these two subtypes of non-small-cell carcinoma." (PMID 31935792, 2020). "A trans-bronchoscopic lung biopsy revealed non-small cell carcinoma of lung origin (positive for TTF-1 and negative for p40)." (PMID 31720896, 2019). "Complete imaging of the right lower lobe (RLL) showed a spiculated mass of about 3.4 × 2.2 cm, and a trans-bronchoscopic lung biopsy revealed non-small cell carcinoma of lung origin (positive for TTF-1 and negative for p40)." (PMID 31720896, 2019). "Further, PDX tissue sections generally did not express antigens characteristic of non-small cell lung cancers, including Keratin 5, Keratin 6, Keratin 7, Keratin 14, Keratin 20, TTF1, TP63, and Napsin A." (PMID 25955027, 2015). "Additionally, focal expression of non-small cell lung cancer (NSCLC) markers like p63, p40, and TTF1 may be observed, while INI-1 expression remains intact." (PMID 38265099, 2024). "In the group of non small cell lung cancer - not otherwise specified, adenocarcinoma phenotype can be determined immunohistochemically using TTF-1 and Napsin A. Expression of oncofetal protein IMP3 in human cancer is associated with poor differentiation and aggressive behaviour." (PMID 23190601, 2012). "One retrospective study demonstrated that TTF-1 expression was a good marker for higher response rates and prolonged PFS and OS in patients with non-squamous, non-small-cell lung cancer." (PMID 31196060, 2019). "Endobronchial ultrasound-guided transbronchial needle aspiration (EBUS-TBNA) of the lung tumor revealed negative staining for TTF-1 and napsin A mucin, and positive staining for p40 and CK5/6, leading to a diagnosis of non-small cell lung carcinoma (NSCLC) that was not otherwise specified (NOS)." (PMID 40491627, 2025). "The biopsy of the right lung nodule diagnosed a non small cell lung cancer (NSCLC), while that of the bone metastases was inconclusive (metastases from adenocarcinoma of unknown origin resulting positive for both cheratin and AE1/AE3 and negative for both TTF1 and PSA)." (PMID 27581366, 2016).
small cell lung carcinoma (36 papers, 2008 to 2025). Small cell lung cancer (SCLC) is a highly aggressive malignant neoplasm, accounting for 10-15% of lung cancer cases, characterized byrapid growth, and early metastasis. "Furthermore, TTF-1 is also associated with the occurrence of small-cell lung cancer (SCLC)." (PMID 34631891, 2021). "In summary, our findings and corroborative studies present a compelling case for the significance of TTF1 in the clinical landscape of small-cell lung cancer." (PMID 39392394, 2024). "In particular, in small cell lung cancer, TTF1 is more likely to be expressed in the peripheral type than in the central type, and is attracting attention as a factor for poor prognosis." (PMID 39292386, 2024). "Malignant melanoma expressed HMB45, MelanA, and S-100; small cell lung cancer expressed TTF-1, CD56, and CgA; hepatocellular carcinoma expressed GPC-3, hepatocyte, and Sall4." (PMID 37608278, 2023). "MCC is negative for leukocyte common antigen (CD45, in contrast to lymphoma), S-100 (in contrast to melanoma), CK7 and TTF-1 (in contrast to small cell lung cancer)." (PMID 32121063, 2020). "A commonly used marker to identify adenocarcinoma is TTF-1 (transcription termination factor 1), but in 70–90% cases of small cell lung cancer, expression of this marker is present." (PMID 29137182, 2017). "An immunopanel including cytokeratin 20 (CK20) and thyroid transcription factor-1 (TTF-1) allows the greatest sensitivity and specificity for excluding small cell lung cancer." (PMID 28138393, 2017). "While TTF-1-expression was found to be frequent in adenocarcinoma and small cell lung cancer, it appears to be rare in patients with squamous or large cell carcinoma." (PMID 25889870, 2015). "In particular, immunohistochemical stains for CK20, TTF-1 and neurofilaments are useful markers for the immunohistochemical distinction between Merkel cell carcinoma from small cell carcinoma of the lung." (PMID 24555167, 2014). "Most of small cell lung carcinomas were positive for TTF-1 (17/20; 85%), and CD56 (18/20; 90%)." (PMID 29531543, 2017). "The aim of this study was to analyze the frequency of Thyroid Transcription Factor (TTF)-1 expression in small cell lung cancer (SCLC) and its value for the diagnosis of SCLC, the response to first line treatment as well as the prognostic impact on overall survival (OS)." (PMID 25889870, 2015). "TTF-1 is a very reliable and accurate diagnostic marker for small-cell lung carcinoma but it is not expressed by Merkel cell carcinoma." (PMID 23691324, 2013). "Subsequent immunohistochemistry after lobectomy confirmed small cell lung carcinoma (SCLC), insofar as that TTF-1 (thyroid transcription factor-1) evidenced a pulmonary origin and Synaptophysin-staining demonstrated neuroendocrine differentiation." (PMID 32450842, 2020). "Small Cell Lung Cancer (SCLC), typically characterized as an undifferentiated cancer, exhibits TTF-1 positivity in 80–90% of cases, indicating a function beyond epithelial cell differentiation." (PMID 39392394, 2024). "Earlier study using RNA ChIP found that the expression of TTF-1 gene was different in LUAD and small-cell lung cancer (SCLC)." (PMID 35646118, 2022). "The aim of this study is to explore roles of thyroid transcription factor-1 (TTF-1), CD56, P40 expression and other clinical characteristics predicting response and survival in patients with small cell lung cancer (SCLC)." (PMID 28855032, 2017). "Small cell lung carcinoma was positive for CTK AE1/AE3, TTF1, and CD56." (PMID 40407482, 2025). "Histochemistry showed TTF-1 was positive, CgA was paranuclear punctate positive, and the urothelial marker GATA3 was negative, which well proved that the source of the kidney tumor in this case was lung small cell carcinoma." (PMID 37161448, 2023).
small cell lung carcinoma (continued). "In small-cell lung cancer, conversely, it has been reported that the prognosis is poor in patients with TTF-1 expression, and there is no doubt that TTF-1 has a role as a prognostic factor and can be a therapeutic target." (PMID 36614938, 2022). "Most low-molecular-weight cytokeratin markers and CK20 will be positive in a perinuclear dot-like pattern, while CK7 and TTF-1 (immunoreactive in >80% of small cell lung cancers) are typically negative." (PMID 28138393, 2017). "Of these, 38/221 (17.2%) had TTF-1 negative small cell lung cancer, whereas 183/221 (82.8%) tumors showed reactivity in TTF-1 immunostaining." (PMID 25889870, 2015). "Additional IHC work up on the archived bioptic material (TTF1, CK7, CK20, chromogranin, synaptophysin, and CD56) resulted in a diagnosis that was in agreement with the 64 microRNA assay first answer of small cell lung carcinoma." (PMID 23758919, 2013). "Negative TTF-1 expression can exclude small-cell lung carcinoma and medullary thyroid carcinoma." (PMID 41245381, 2025). "All TTF-1-negative small cell lung carcinoma (SCLC) cases had a full report review by pathologists." (PMID 37139017, 2023). "Positive CK20 and negative TTF-1 and CK7 distinguish the tumor cells from small cell lung carcinoma." (PMID 27814751, 2016). "Another characteristic is also the absence of expression of thyroid transcription factor-1 (TTF-1) and CK7, usually present in small-cell lung cancer, of leucocyte common antigen (LCA) which is positive in lymphoma, and of S100 and HMB45, which are positive in melanoma." (PMID 36612102, 2022).
papillary thyroid carcinoma (33 papers, 2008 to 2026). "The histologic examination revealed a well differentiated papillary carcinoma, classical variant, with multiple microscopic foci in both lobes of the thyroid gland; the tumor stained positively for TTF1 and Thyroglobulin." (PMID 28810922, 2017). "Pathology showed papillary thyroid carcinoma with strong and diffuse staining for TTF-1 and thyroglobulin." (PMID 35096430, 2022). "report, TTF-1 expressed nearly 100% of papillary thyroid carcinomas, follicular carcinomas, and follicular adenomas." (PMID 36329478, 2022). "Caution should be taken to differentiate TL-LGPPA from other TTF-1-positive neoplasms, especially papillary thyroid carcinoma, as the prognosis for these two tumors is entirely different." (PMID 32015924, 2020). "TTF1 was over-expressed in samples of human anaplastic thyroid cancer; whereas, it was down-regulated in follicular and undetectable in papillary thyroid cancer." (PMID 29561759, 2018). "The presumptive existence of a new subset of nephroblastoma displayed papillary thyroid carcinoma-like histology along with TTF-1 and TG immunoexpressions." (PMID 28328844, 2017). "TTF-1 is also a sensitive marker for papillary carcinoma of the thyroid, although it is estimated that fewer than 1% of patients with papillary thyroid carcinoma have malignant pleural effusions." (PMID 26806377, 2016). "In papillary thyroid carcinomas the reactivity of TTF-1, thyroglobulin, and CK7 is essentially 100%." (PMID 27774331, 2016). "Negativity for TTF-1 and thyroglobulin expression, which are markers for follicular and papillary carcinomas, as well as for calcitonin, a marker of medullary thyroid carcinoma, excluded the possibility of these tumors, more commonly found in the thyroid." (PMID 25295208, 2014). "First, from a fundamental point of view, this work demonstrates for the first time that Wnt/β-catenin regulates TTF-1 in papillary thyroid cancer cells through β-catenin-binding to a TCF/LEF-responsive element present in TTF-1 promoter." (PMID 21814573, 2011). "Quantitative reverse transcription-polymerase chain reaction (RT–PCR) showed decreased expression of HNF3β/FoxA2 and TTF-1 mRNA in papillary thyroid carcinoma cell lines, when compared with normal thyroid cells." (PMID 18682709, 2008). "Next, we transfected either the HNF3β/FoxA2 or the TTF-1 expression vector into papillary thyroid carcinoma cell lines." (PMID 18682709, 2008). "We found TL-LGNPPA and papillary thyroid carcinoma were positive for TTF-1 and CK19." (PMID 36705380, 2023). "Thyroid transcription factor 1 (TTF-1) may be localized to the nucleus in differentiated thyroid carcinoma with increased frequency in the settings of recurrent or persistent disease." (PMID 25292307, 2015). "The aim of this study is to investigate whether the Wnt/β-catenin pathway could regulate TTF-1 expression in a papillary thyroid carcinoma model and to examine the mechanism(s) involved in this regulation." (PMID 21814573, 2011). "Reporter gene analysis found that the promoter region of TG, TPO, and TSHR could be activated by the forced expression of either Pax-8 or TTF-1 in the papillary thyroid carcinoma cell line NPA." (PMID 18682709, 2008). "Furthermore, not only papillary thyroid carcinoma but also MTC show expression of TTF-1." (PMID 27409604, 2016). "Metastasis was identified in a lymph node at the mediastinum, supporting a diagnosis of usual-type papillary thyroid carcinoma, with positivity for cytokeratin AE1/AE3, thyroglobulin, and TTF-1." (PMID 39553134, 2024). "The lung nodules were biopsied and revealed papillary thyroid carcinoma with psammomatous calcifications and PAX8, TTF-1, and thyroglobulin immunostaining were reported as positive." (PMID 27774331, 2016). "First, we verified the TTF-1 expression in the human TPC-1 cell line and in human papillary thyroid carcinoma by qRT-PCR and immunofluorescence." (PMID 21814573, 2011).
papillary thyroid carcinoma (continued). "Histology, however, revealed papillary carcinoma with focal solid mucin producing regions positive for CK19 and HBME and weakly positive for TTF1 and thyroglobulin." (PMID 19495405, 2009). "Metastasis was identified in a lymph node, supporting the diagnosis of usual-type metastatic papillary thyroid carcinoma, with positivity for cytokeratin AE1/AE3, thyroglobulin, and thyroid transcription factor 1 (TTF-1), confirming usual-type metastatic papillary carcinoma." (PMID 39553134, 2024). "This makes unlikely to assume metastasis from the well differentiated papillary carcinoma, that stained positively for TTF1 and thyroglobulin and surgically removed nine years earlier." (PMID 28810922, 2017). "After isolation, CD133+ cells exhibited higher radioresistance and higher expression of Oct4, Nanog, Sox2, Lin28 and Glut1 in the cell line or primarily cultured papillary thyroid cancer cells, and lower expression of various thyroid-specific genes, namely NIS, Tg, TPO, TSHR, TTF1 and Pax8." (PMID 23081821, 2013). "The localization of TCF-4 and TTF-1 in the same area of PTC tissues might be of clinical relevance, and justifies further examination of these factors in the papillary thyroid cancers follow-up." (PMID 21814573, 2011). "Interestingly, immunohistochemical studies performed on four papillary thyroid carcinomas and three normal thyroid tissues taken at distance of benign adenoma showed a TCF-4 and TTF-1 positive expression and localized in nuclei in normal tissue as well as in PTC." (PMID 21814573, 2011). "Finally, the localization of TCF-4 and TTF-1 in the same area of PTC tissues might also be of clinical interest, and justifies further examination of these factors in the follow-up of papillary thyroid cancer." (PMID 21814573, 2011). "Recently, we have demonstrated that TAZ acts as a potent regulator of Pax8 and TTF-1 activity and we have also reported that TAZ, already known to promote cell proliferation and to induce epithelial–mesenchymal transition, is overexpressed in papillary thyroid cancer." (PMID 21966443, 2011).
neuroendocrine tumors (26 papers, 2012 to 2025). "SCC usually exhibits pronounced keratinization and intercellular bridges and is diffusely positive for P63 and P40; adenocarcinoma is positive for TTF-1, napsin-A and neuroendocrine tumors are positive for CD56, synaptophysin, and chromogranin." (PMID 40746613, 2025). "Our data also enabled an assessment of the previously proposed utility of TTF-1 IHC for the distinction of pulmonary from extrapulmonary neuroendocrine neoplasms and demonstrated that this separation can best be made in highly differentiated tumors." (PMID 39377914, 2024). "Consistent with the fact that SCLC is a malignant neuroendocrine tumor of lung origin, the expanded CTCs were positively stained for neuroendocrine marker synaptophysin and lung tumor marker TTF-1." (PMID 33207745, 2020). "With regard to lung neuroendocrine tumors, the relevance of TTF-1 expression to tumor location has also been shown in carcinoids." (PMID 26705222, 2015). "Notably, neuroendocrine tumors can show TTF-1- and Napsin-A positivity across various primary tumor sites, including the gastrointestinal tract." (PMID 40564811, 2025). "Neuroendocrine tumors arising in other organs are also positive for TTF-1." (PMID 24062959, 2013). "Thyroid transcription factor-1 (TTF-1) stains positive in 28–69% of lung carcinoids and may help in the differential diagnosis between a primary lung carcinoid and metastasis from a neuroendocrine tumor located elsewhere." (PMID 38001701, 2023). "In our cases, cytokeratin 7, TTF-1, p63, and p40 for lung tumors; CK7, GATA3, and GCDFP-15 for breast tumors; and cytokeratins, synaptophysin, chromogranin, and CD56 for neuroendocrine tumors were the most used markers." (PMID 35308701, 2022). "In few studies the utility of markers indicating the origin of neuroendocrine tumors, such as cytokeratin CK20, CK7, thyroid transcription factor (TTF-1) and CDX-2 in ovarian neuroendocrine tumors were determined." (PMID 34917031, 2021). "However, the specificity was increased considerably for TTF-1 (both clones), p40, p63 and CK5 if the neuroendocrine tumors were excluded in the calculations." (PMID 30718697, 2019). "The 41 cases (6% of 657) with negative p40 and TTF-1 and no obvious keratinization or glands consisted of 12 AC, 10 SqCC, 8 LCC, 8 neuroendocrine tumors and 3 sarcomatoid carcinomas." (PMID 30718697, 2019). "Thyroid transcription factor 1 (TTF-1), a marker for metastases in NETs of pulmonary origin, and CDX2, a marker for metastases of gastrointestinal origin, were mostly negative in presacral neuroendocrine tumors." (PMID 34690926, 2021). "Among the 41 cases with negative p40 and TTF-1 and no obvious keratinization or glands, CK7 was positive (≥50% of the cells in all cases with any positivity) in 10 of the 12 AC, 7 of the 10 SqCC, 5 of the 8 LCC, 2 of the 8 neuroendocrine tumors and 2 of the 3 sarcomatoid carcinomas." (PMID 30718697, 2019).